LGALS9 (galectin 9)
Diseases named in the same sentence as LGALS9 in open-access papers (continued):
Sharing a sentence is not in itself a finding about the gene and the disease.
tumor (continued). "Furthermore, according to the results of multiple logistic regression, the Lauren type is an independent feature, while tumor differentiation degree is associated with the expression of LGALS9 as a secondary characteristic." (PMID 36430322, 2022). "Thus, the expression of the LGALS9 gene is associated with the Lauren type, while the degree of tumor differentiation is a secondary (tumor-type dependent) characteristic." (PMID 36430322, 2022). "g. tumour-associated macrophages) present in the tumour microenvironment where the released TGF-β may activate galectin-9 expression in cancer cells." (PMID 34234778, 2021). "Galectin-9 (Gal-9) is an immune checkpoint protein that facilitates T cell exhaustion and modulates the tumor-associated microenvironment, and could be a potential target for immune checkpoint inhibition." (PMID 34680500, 2021). "Blocking the secretion of exosomal LGALS9 from GBM tumors could cause mice to exhibit sustained DC tumor antigen-presenting activity and long-lasting antitumor immunity." (PMID 33093453, 2020). "Tumor-associated macrophages and monocytic MDSCs had little expression of galectin-9." (PMID 32055023, 2020). "Expression of galectin-9 in solid tumors has been linked to tumor cell adhesion or metastasis." (PMID 29389859, 2018). "The function of galectin-9 in tumor associated macrophages requires further investigation." (PMID 26066796, 2015). "This could promote tumor metastasis especially if loss of galectin-9 in tumor cells results in loss of tissue integrity." (PMID 25259711, 2014). "Loss of galectin-9 expression could compromise tissue integrity allowing tumor cells to intravasate into circulation and metastasize." (PMID 25259711, 2014). "The Tim-3 ligand, galectin-9, has been linked with tumor progression." (PMID 23526963, 2013). "However, IFN-γ-induced expression of galectin-9 in tumor-associated macrophages promotes Tim-3+ Treg expansion, which in turn eliminates and dampens the effects of Teffs in the tumor nest." (PMID 23526963, 2013). "In this study, we found that Tim-3 is specifically expressed on tumor-associated Tregs, which may render these cells susceptible to regulation by galectin-9." (PMID 23526963, 2013). "In addition to lactate production by tumor cells through the Warburg effect, the secretion of LGALS9 (encoding the galactoglucan lectin-9 protein, Gal-9) and epidermal growth factor (EGF) by tumor cells is essential for inducing the polarization of TAMs into M2 TAMs." (PMID 39889181, 2025). "Similarly, LGALS9 encodes human galectin-9, which is expressed in various tumor cells." (PMID 31952466, 2020). "Thus, in MDS patients, galectin-9 may induce T-cell apoptosis through Tim-3, which could be associated with tumor progression with immune escape." (PMID 29179486, 2017). "Among them, Galectin-1, Galectin-3, and Galectin-9 have been most extensively investigated for their multifaceted roles in shaping the tumor microenvironment." (PMID 42129932, 2026). "The transcriptomic analysis brought to light that a molecular signature of dysfunctional CD8+ positively correlates with tumor LGALS9, supporting that Gal-9 is associated with CD8+ dysfunction in GC." (PMID 40666515, 2025). "Our analysis identified a GALECTIN pathway present in these two T‐lineage tumours, LGALS9 signals emitted from DN and DP cells interact with the HAVCR2 receptor on CD8+T cells and the CD44 receptor on Tregs." (PMID 40579780, 2025). "For instance, NPC-derived EVs, decorated with membrane-bound galectin-9, a ligand of the membrane receptor Tim-3, induce Th1 cell apoptosis to mitigate anti-tumor T cell responses." (PMID 40908470, 2025). "Then, DNMT3A binds to promoters of HAVCR2 and LGALS9 genes, increasing the methylation levels in these promoters and decreasing the expression of Tim-3 and Galectin-9 in SiHa and HeLa CC cells, as well as in vivo tumor growth." (PMID 41226543, 2025).
tumor (continued). "The TIM3/LGALS9 interaction is recognized for its immunosuppressive effects, which tumors can exploit to circumvent immune surveillance, thereby promoting tumor progression and correlating with poor prognosis in cancer patients." (PMID 41194934, 2025). "For example, galectin-9 overexpression triggers the shedding of galectin-9 positive exosomes from tumor cells and supports angiogenesis." (PMID 40475972, 2025). "The interaction with one of its ligands, namely galectin-9 (Gal-9), has been shown to induce immune cell death, promotes tumor growth, and suppresses adaptive immune responses." (PMID 40148963, 2025). "Our earlier study shows that LGALS9 binds with myeloid cells and promotes a tumor-supportive microenvironment." (PMID 41271007, 2025). "In line with these mechanistic findings, LGALS9 expression is higher in tumor compared to respective normal tissue across many cancer types." (PMID 40775219, 2025). "Then the CXCL5-CXCR2 and LGALS9-HAVCR2 were identified in the cell-cell communication between CXCL5+ SLC6A14+ tumor cells and MRC1+ macrophages." (PMID 39670859, 2025). "Given its broad spectrum of activity—from modulating dendritic cell phenotype to regulating T cell viability—Galectin-9 has emerged as a promising therapeutic target in both inflammatory and neoplastic diseases." (PMID 40806347, 2025). "Exogenous galectin-9 rescued the motility of tumor-immunocompromised human blood DCs, validating the physiological relevance of galectin-9 in DC migration." (PMID 40986321, 2025). "WT DCs enhanced their migratory capacity both upon maturation and when present in the vicinity of a tumor, whereas this increase was only marginal in gal9 KD DCs, suggesting that galectin-9 has a broad impact on the capacity of DCs to migrate." (PMID 40986321, 2025). "As LGALS9 and HAVCR2 genes are associated with immune regulation, we evaluated the correlation of these transcripts’ abundance with the gene signature of tumor microenvironment cells Cibersort ABS on TIMER®." (PMID 40666515, 2025). "Lastly, data presented here highlight a role of galectin-9 in promoting DC motility in the tumor microenvironment, underscoring galectin-9 as a target in DC-mediated antitumor immunity." (PMID 40986321, 2025). "Analysis of DC motility in the 3D tumor microenvironment revealed galectin-9 is also required for DC recruitment and infiltration." (PMID 40986321, 2025). "The TIM-3/Galectin-9 axis impairs CD8 + tumor-infiltrating lymphocytes (TIL) function and correlates with chemotherapy resistance." (PMID 40186663, 2025). "Subsequently, low DNMT3A expression decreases methylation levels in HAVCR2 and LGALS9 promoters, promoting Tim-3 and Galectin-9 expression in HeLa and C-33A CC cells, suppressing the anti-tumor immunity mediated by innate and adaptive immune cells." (PMID 41226543, 2025). "Tim-3 and its receptor, galectin-9 (Gal-9), have emerged as novel targets in recent studies on tumor immune checkpoints." (PMID 41019058, 2025). "Blockade of galectin-9 in vitro and in mouse models results in enhanced T-cell survival and improved anti-tumor immunity, especially in combination with co-stimulatory anti-GITR treatment." (PMID 40775219, 2025). "IHC confirmed tumor cells expressed LGALS9 with a trend for higher expression in the P2 (immune-hot) subtype." (PMID 41332664, 2025). "Exogenous galectin-9 was able to rescue the impaired migration capacity of tumor-immunocompromised human blood DCs, confirming the relevance of galectin-9 in DC motility and highlighting the physiological and translational relevance of our findings." (PMID 40986321, 2025). "Blockade of galectin-9 and Tim-3 using neutralizing antibodies reduces the interaction between TEVs and Th1 cells, thereby elevating anti-tumor T cell responses." (PMID 40908470, 2025). "The immune checkpoint molecule TIM-3 and its ligand galectin-9 (Gal-9) contribute to T cell exhaustion, impairing anti-tumour immunity." (PMID 41296385, 2025).
tumor (continued). "The tumor microenvironment (TME) in T-ALL is immunosuppressive with an overexpression of the immunosuppressive proteins such as galectin-9 which inhibits the tumor-specific immune response." (PMID 40550858, 2025). "Here, we demonstrate that exposure of cDC2s to tumor CM induced galectin-9 downregulation and impaired cell migration." (PMID 40986321, 2025). "Compared to HVs, all three neoplasms showed an increased sCD25, sLAG3, Galectin-9 and sB7.2 expression, while gastrointestinal and pancreatic NENs shared higher levels of IL6 and MCP-1." (PMID 40038821, 2025). "How galectin-9 shapes the immune compartment within the tumor microenvironment has scarcely been addressed despite its relevant role driving tumorigenic processes." (PMID 40986321, 2025). "Galectin-9 (LGALS9) also inhibits the anti-tumor effect of T and NK cells, where it binds to TIM-3 as an inhibitory ligand." (PMID 40699665, 2025). "Galectin-9 rescued the motility of tumor-immunocompromised dendritic cells, validating the physiological relevance of our data and underscoring its implications for DC-based immunotherapies." (PMID 40986321, 2025). "Galectin-9 (Gal-9) is a glycan-binding protein (lectin) representing an attractive new cancer immunotherapeutic target owing to its pleiotropic roles in immune and tumor cell-intrinsic functions, including in activation, proliferation, and trafficking." (PMID 40869319, 2025). "In accordance with our results, a recent study described a novel immunosuppressive subtype of senescent tumor cells that exerted an inhibitory effect on immune cells, including mast cells, myeloid cells, NK cells, B cells, and T cells via LGALS9 signaling." (PMID 40362421, 2025). "Both HAVCR2 and LGALS9 expression levels were significantly higher in tumor compared to normal tissue." (PMID 41323263, 2025). "Our findings align with previous work demonstrating that LGALS1, LGALS3, and LGALS9 bind to glycosylated ligands on T cells, inducing apoptotic cell death and attenuating anti-tumour immune responses." (PMID 41516291, 2025). "Galectin-9 (Gal-9) is a tandem-repeat lectin with complex and dualistic roles in tumor progression and immune regulation." (PMID 40710343, 2025). "The expression of LGALS9 in CAFs indicates a potential involvement in the tumor microenvironment through its interaction with T cells." (PMID 40358847, 2025). "Galectin-9, through interaction with Tim-3, modulates tumor immunity; blockade of the Gal-9/Tim-3 axis elicits anti-tumor immune responses and suppresses tumor growth." (PMID 40895569, 2025). "TIM-3 inhibits T-cell activity and proliferation, promotes immune tolerance, and reduces the anti-tumor effect of T cells by binding to its ligands, such as Galectin-9." (PMID 40429702, 2025). "The expression of ligands, including TNFRSF14, CD274, and LGALS9, on tumor cells increased in the LN-out group." (PMID 38519500, 2024). "Endothelial expression of galectin-9 has also been reported to be increased in the tumor vasculature." (PMID 38990363, 2024). "Lgals9 (Galactose lectin 9), a member of the galactose lectin family, is a widely expressed protein that is involved in immunomodulation and tumor pathogenesis and influences the prognosis of many types of cancers." (PMID 38992056, 2024). "The Galectin-9-dependent tumor-suppressive functions of ATXN3 were further corroborated by a wound healing assay." (PMID 38815863, 2024). "It has been found that blocking Galectin-9 can induce anti-tumor immunity and reverse the exhaustion of effector T cells." (PMID 38338674, 2024). "For example, we observed significantly elevated galectin-9 expression in the tumor endothelium of lung, liver and kidney cancer compared to healthy tissues." (PMID 38990363, 2024). "Intriguingly, the targeted removal of the ATXN3 gene led to a noteworthy decrease in the protein expression of Galectin-9, a carbohydrate-binding protein known for modulating immune response, inhibiting tumor cell growth, and inducing apoptosis." (PMID 38815863, 2024).
tumor (continued). "Galectin-9 is secreted by cancer and myeloid cells upon induction by interferon β and γ (IFNβ and IFNγ) and has immunosuppressive roles in the tumor microenvironment." (PMID 38195762, 2024). "While the observed activities indicate an immunostimulatory function there is increasing interest in the immunosuppressive activity of galectin-9, in particular in the context of tumor immune escape." (PMID 38990363, 2024). "Blocking exosomal LGALS9 allows sustained tumor antigen presentation and durable anti-tumor immune activity in GBM." (PMID 38720342, 2024). "TIM3 induces CD8+TILs exhaustion and inhibits its anti-tumor function mainly by binding to its ligands (Galectin-9, HMGB1, CEACAM1, and Ptdser)." (PMID 38369502, 2024). "Crucially, the restoration of Galectin-9 expression completely countered the increase in ATXN3-null cancer cell growth, unequivocally demonstrating that ATXN3 executes its tumor-suppressive functions through the upregulation of Galectin-9." (PMID 38815863, 2024). "For example, FLRT3 is reported to be involved in the prevention of anti-tumor immunity via Tim-3-Galectin-9 pathway." (PMID 38225404, 2024). "Further immunohistochemistry staining confirmed a significant reduction in Galectin-9 expression levels in the xenograft tumor tissues." (PMID 38815863, 2024). "Disruption of the Dectin-1-galectin-9 signaling axis restores the anti-tumor activity of CD4+ and CD8+ T cells." (PMID 39590166, 2024). "The blockade of TIM3/Galectin-9 pathway, to potentiate the anti-tumor function of CD8+TILs and eradicate malignant cells has already revolutionized the treatment of many solid tumors while rare in DLBCL." (PMID 38369502, 2024). "HIF-1α upregulates the expression of various immunosuppressive molecules in tumor cells, including galectin-9 (Gal-9)." (PMID 38542288, 2024). "The Dectin-1/galectin-9 signaling axis plays a critical role in forming an immune-suppressive tumor microenvironment in PDAC." (PMID 39590166, 2024). "By loading galectin-9 siRNA into exosomes and surface modification of exosomes with oxaliplatin prodrug as an immunogenic death trigger, therapeutic exosomes can improve tumor targeting and increase drug accumulation at tumor sites." (PMID 39100671, 2024). "With regard to the role of endothelial galectin-9 in tumor angiogenesis also little information is available." (PMID 38990363, 2024). "LGALS9 mRNA, upregulated 16.5-fold in tumor tissue, produces Galectin-9 protein that interacts with tumors independently to influence tumor progression, functioning as an immune checkpoint and merging as a target for immunotherapy." (PMID 39457004, 2024). "Since most studies were performed using in vitro models or in the context of developmental angiogenesis, more research is required to further unravel the contribution of endothelial galectin-9 to tumor angiogenesis." (PMID 38990363, 2024). "Studies discovered that Gal-9 expressed by tumor cells or APCs (DCs) induced T cell apoptosis via Galectin-9/TIM-3 pathway." (PMID 38366083, 2024). "Gene expressions for tumor promoting genes such as Arg1, Il6, Il10, Mmp9, Lgals9, and Vegfa were significantly decreased, whereas that of the tumor suppressive gene such as Il12 increased." (PMID 39702544, 2024). "Its interaction with its soluble ligand, galectin-9, which is secreted by tumor cells, leads to the suppression of T-cell activation." (PMID 39199554, 2024). "The interaction between TIM-3 and galactoglucan lectin 9 (LGALS9) has been shown to induce apoptosis in Th1 cells, thereby reducing anti-tumor immune responses." (PMID 39232806, 2024). "TIM-3 is a type I trans-membrane protein, and its primary ligands include Galectin-9, the most studied ligand and crucial regulator of tumor cell immune evasion." (PMID 38927447, 2024). "Galectin-9 (gal-9) is peculiar in that studies demonstrate its ability to act as a tumor-promoting and anti-tumor protein." (PMID 38927753, 2024).
tumor (continued). "Galectin-9 is recognized for its tumor-suppressive roles, promoting cancer cell apoptosis and inhibiting cancer cell growth, suggesting a tumor-inhibitory role for the Galectin-9 deubiquitinase ATXN3." (PMID 38815863, 2024). "In short, this study showed a marked protumorigenic role for mast cells in TC and uncovered a novel mechanism by which tumor-infiltrating mast cells intervene in tumor growth via galectin-9." (PMID 37042867, 2023). "In a melanoma model, it has been demonstrated that the TIM3 ECs promote tumor cell proliferation, survival and migration by activating NF-κB in tumor cells in a galectin-9-independent manner." (PMID 37666809, 2023). "These receptors bind to their ligand, the C-type lectin Galectin-9 (Gal-9), which is highly expressed in tumor cells." (PMID 36672492, 2023). "As immunosuppression is a hallmark of cancer, we detected mast cells with an immunosuppressive phenotype in TC and revealed that tumor-infiltrating mast cells showed high levels of the immunosuppressive molecule galectin-9." (PMID 37042867, 2023). "PD-1 interacted with its ligands (PD-L1 or PD-L2) on the tumor cell surface, while Tim-3 mainly interacted with Galectin-9." (PMID 36991376, 2023). "One such study using engineered exosomes isolated from MB-MSC that were loaded with galectin-9 siRNA showed enhanced level of tumor targeting efficacy and tumor suppressive effects on a pancreatic cancer model." (PMID 36674525, 2023). "At the early stage of YUMM3.3 tumor growth examined here, Activin-A secretion increased the expression of the ligands Lgals3, Hmgb1, Lgals9, CD274 in various cell types." (PMID 38304252, 2023). "2.The interaction between the immune checkpoint proteins CD24 and LGALS9 in tumor epithelial cells, SIGLEC10 in dendritic cells, SIGLEC10 and HAVCR2 in macrophages increased." (PMID 37671151, 2023). "LGALS9 gene which is upregulated in PDAC tumor samples in comparison to healthy samples was also found to be upregulated in TAMs compared to tumor-suppressor immune cells in cancer samples." (PMID 37945567, 2023). "Increased TIM-3 expression in tumor cells delivered by plasma EXOs can negatively regulate antitumor responses and accelerate tumor progression through activation of Galectin-9." (PMID 37680720, 2023). "At present, some reports have confirmed the role of galectin-9 in cell cycle regulation, tumor cell adhesion and angiogenesis, metastasis, and tumor immune escape." (PMID 37042867, 2023). "A survey of immune checkpoint receptor ligands revealed upregulation of Lgals3 in fibroblasts, Hmgb1 in tumor cells, and Lgals9 and Cd274 across cell clusters." (PMID 38304252, 2023). "In a previous analysis, enhanced tumor expression of galectin-9 correlated with a better prognosis of patients with HCC." (PMID 37047155, 2023). "Among the four known ligands of TIM-3, the first and most studied is galectin-9 (gal-9), which induces the apoptosis of Th1 cells, playing a crucial role in tumor cell immune evasion." (PMID 37371818, 2023). "We have previously reported that galectin-9 induces apoptosis in various gastrointestinal cancers and suppresses tumor growth." (PMID 37047155, 2023). "TIM-3-binding galectin-9 attenuates T cell expansion and effector functions in the tumor microenvironment." (PMID 36768365, 2023). "Galectin-9 (Gal-9), a member of the β-galactoside-binding protein family, has been demonstrated to induce T-cell death and promote immunosuppression in the tumor microenvironment." (PMID 37781042, 2023). "Galectin-9 can be produced by diverse cell types, including lymphocytes, tumor cells, and endothelial cells." (PMID 37082729, 2023). "Galectin-9 expression is frequently altered in cancer and involved in several aspects of tumor progression, making galactin-9 an interesting potential prognostic marker and a therapeutic target for several malignancies." (PMID 36768365, 2023).